AKT1 (AKT serine/threonine kinase 1)
Diseases named in the same sentence as AKT1 in open-access papers (continued):
Sharing a sentence is not in itself a finding about the gene and the disease.
Obesity (continued). "Through a network pharmacology analysis, the anti-obesity effect of hispidulin was predicted to act on estrogen, prolactin, Rap1, and PI3K-Akt signaling pathways by targeting AKT1, SRC, EGFR, and GSK3B." (PMID 34944408, 2021). "The integration of metabolomics and network pharmacology has identified six hub targets, namely AKT1, EGFR, ESR1, STAT3, IGF1, and MAPK1, that may be critical for the effects of EGCG on obesity-related precocious puberty." (PMID 40807299, 2025). "According to the results of integrated metabolomics and network pharmacology, 6 hub targets, including AKT1, EGFR, ESR1, STAT3, IGF1, and MAPK1, may play significant roles in the effects of EGCG on obesity-related precocious puberty." (PMID 37334310, 2023). "The integrated metabolomics and network pharmacology indicated that AKT1, EGFR, ESR1, STAT3, IGF1, and MAPK1 may be key targets for EGCG in preventing obesity-related precocious puberty." (PMID 37334310, 2023). "In contrast, PPAR signaling pathway of CS on obesity is a sole activator mechanism, not related to AKT1." (PMID 34889899, 2021). "For example, we observed that deletion of Akt1, but not Akt2, significantly blocked DJ-1 transgene-induced glucose intolerance and obesity." (PMID 28224045, 2017). "Additionally, although beta-sitosterol, α-amyrin, and phyllanthin were found not to interact with AKT1 and PPARG genes, they still showed potential for reducing the risk of obesity and warrant further exploration." (PMID 39409084, 2024).
bladder cancer (177 papers, 2006 to 2026). "Somatic mutations in AKT1 have been identified in breast, colorectal, ovarian, LC, and bladder cancer." (PMID 40041495, 2025). "The present study was planned to evaluate the mutational status of PIK3CA and AKT1 genes in bladder cancer patients and to assess the association between these mutations and patients ́ clinico-pathological features." (PMID 35317488, 2022). "The findings revealed that PIK3CA rs6443624 C>A and AKT1 rs2498801A>G variants caused a significant decline in the risk developing bladder cancer." (PMID 29383014, 2018). "The Akt1 G49A (E17K) mutation was found in 2/44 (4.8%) of bladder cancer cell lines and 5/184 (2.7%) of bladder tumors." (PMID 25414595, 2014). "AKT1 mutations also can be involved in bladder cancer development as well as germ line genetic variants in RAPTOR." (PMID 21283818, 2011). "Apart from mutations activating AKT1 in several cancers, including bladder, there are limited data regarding its expression in urinary bladder cancer." (PMID 21483670, 2011). "AKT1 is highly expressed in bladder cancer and is associated with its malignant progression." (PMID 41287122, 2025). "In the present study, mutation of AKT1 gene is a rare event in bladder cancer in Moroccan patients." (PMID 35317488, 2022). "In conclusion, our findings suggest that PIK3CA rs6443624, AKT1 rs2498801, AKT1 rs1130233, as well mTOR rs2295080 polymorphism may be related to bladder cancer development in a sample of Iranian population." (PMID 29383014, 2018). "Therefore, this case-control study was designed to assess the possible association between PIK3CA, AKT1 and mTOR polymorphisms and susceptibility to bladder cancer in an Iranian population." (PMID 29383014, 2018). "The results showed that the expression level of AKT1 in bladder cancer was positively correlated with tumor purity, infiltration abundance of CD4 + T Cell, Macrophage, Neutrophil and Dendritic Cell." (PMID 41287122, 2025). "Considering that in the present work, AKT1 was identified as the target of COP, it is reasonable to suppose that COP represses the activation of PI3K/AKT signaling and the related malignant behaviors of bladder cancer cells via directly suppressing AKT1." (PMID 41287122, 2025). "NAT10 mediates ac4C modification of oncogenes (BCL9L, SOX4, and AKT1) in bladder cancer to enhance their mRNA stability, thereby promoting cancer cell malignant behaviors and stem-cell-like properties." (PMID 40999468, 2025). "NAT10 mediates ac4C acetylation of BCL9L, SOX4, and AKT1, enhancing their mRNA stability and promoting proliferation, migration, and stemness while inhibiting apoptosis in bladder cancer." (PMID 39640362, 2024). "That is, sulforaphane inhibits glucose metabolism mediated by the AKT1/HK II axis, and treats bladder cancer." (PMID 38202657, 2023). "A previous study showed that the replacement of miR-143-3p in bladder cancer cells reduced AKT1 levels, an effect that was further enhanced by simultaneously restoring miR-145-5p, a miRNA family member of miR-143-3p." (PMID 37759434, 2023). "Others reported that the constitutive activation of AKT1 led to the inhibitory effect of curcumin on cell proliferation and migration in human bladder cancer." (PMID 36297027, 2022). "To summarise, the dynamic accommodation of BCL9L, SOX4 and AKT1 transcripts mediated by NAT10‐dependent ac4C modification is critical for the progression of bladder cancer." (PMID 35522942, 2022). "In a prospective study of bladder cancer, mutations of the PIK3CA and AKT1 genes, the main players in the PI3K-AKT-mTOR signalling pathway (which plays a significant role in cell growth, proliferation, and survival), were examined." (PMID 35955727, 2022). "We found that the combined expressions of Bcl-w or Akt1 proteins were significantly increased in bladder cancer specimens compared to adjacent normal tissues (P < 0.01 for both)." (PMID 25414595, 2014).
bladder cancer (continued). "In our study, the expression of Bcl-w and Akt1 proteins in 41 bladder cancer specimens and adjacent normal tissues was detected by Western blot assay." (PMID 25414595, 2014). "We found that Bcl-w and Akt1 proteins were significantly overexpressed in bladder cancer tissues versus adjacent normal tissues." (PMID 25414595, 2014). "In this study, we detected the expression of miR-133b, Bcl-w and Akt1 in clinical bladder cancer tissues." (PMID 25414595, 2014). "Bcl-w and Akt1 protein expression was detected by Western blot in 41 bladder cancer specimens and adjacent normal tissues." (PMID 25414595, 2014). "Bcl-w and Akt1 protein expression in 41 bladder cancer specimens and adjacent normal tissues was detected by Western blot." (PMID 25414595, 2014). "Bcl-w and Akt1 proteins were significantly overexpressed in bladder cancer tissues versus adjacent normal tissues (P < 0.01 for both)." (PMID 25414595, 2014). "We found Bcl-w and Akt1 to be putative targets of miR-133b and show increased expression of these proteins in bladder cancer tissues." (PMID 25414595, 2014). "The effects of miR-133b mimics or an inhibitor on levels of Bcl-w and Akt1 mRNA and protein in a human bladder cancer cell line, T24, were studied." (PMID 25414595, 2014). "After transfection of miR-133b mimics or inhibitor into a T24 human bladder cancer cell line, Bcl-w and Akt1 protein and mRNA expression were examined by Western blot and RT-PCR, respectively." (PMID 25414595, 2014). "In bladder cancer, activation of AKT1-mediated survival has only been shown in TCCSUP cells in culture." (PMID 16412233, 2006). "Similarly, NAT10 stabilizes BCL9L, SOX4, and AKT1 transcripts in bladder cancer through 3'UTR ac4C modification, fueling proliferation and invasion." (PMID 40588654, 2025). "Additionally, the AKT1 promoter is nearly demethylated in bladder cancer tissues, and the methylation level of AKT1 is found to be clinically correlated with bladder cancer." (PMID 36430344, 2022). "Studies have shown that Akt1 is almost completely hypomethylated in bladder cancer tissues." (PMID 30872976, 2019). "Recent reports have identified that abnormal methylation of the Akt1 gene may be an early event during urocystic tumorigenesis and this should be further evaluated as a tumorigenesis marker for early detection of bladder cancer." (PMID 25414595, 2014). "We show mi-R133b regulated Bcl-w and Akt1 in cultured T24 cells and we therefore speculated that miR-133b affects the biological behavior of bladder cancer by regulating the expression of Bcl-w and Akt1." (PMID 25414595, 2014). "The functional role of miR-133b in bladder cancer and its influence on Bcl-w and Akt1 protein and mRNA expression, and cell proliferation and apoptosis, was studied after transfection of miR-133b mimics or inhibitor into a transitional human bladder carcinoma cell line, T24." (PMID 25414595, 2014). "Previous reports have shown that Akt1 is involved in the regulation of bladder cancer; however, it is unclear whether miR-133b can regulate the expression of Akt1 in T24 human bladder cancer cells." (PMID 25414595, 2014). "Activation of the AKT1 survival pathway on Matrigel suggests this pathway could be relevant to clinical bladder cancer." (PMID 16412233, 2006). "Notably, this study found that the expression levels of AKT1, GSK3B, CASP3, TNF, and CCND1 were associated with immune cell infiltration in bladder cancer, suggesting that these targets could be used as potential predictors of bladder cancer immunotherapy." (PMID 41287122, 2025). "In conclusion, this study is very informative and clearly showed that mutations in AKT1 and PIK3CAare rare events and could not be considered as valuable biomarkers for bladder cancer management." (PMID 35317488, 2022). "Also, PEPE2 treatment might interfere with the HSP90/Akt-1/ASK-1 cascade to provoke apoptosis in the bladder cancer cell." (PMID 36362994, 2022).
bladder cancer (continued). "The down-regulation of NAT10 results in the reduction of ac4C modification in specific regions of mRNA, impairing translational efficiency of BCL9L, SOX4, AKT1 as well as the stability of BCL9R and SOX5, thereby reducing bladder cancer burden." (PMID 38233839, 2024). "However, a previous study on bladder cancer detected a mutation in the PH domain, namely (E49K), which was demonstrated as an enhancer activation mutation that transforms activity in NIH3T3 cells, proposing cooperative enhancement of the AKT1 when it tandemly contains E17K hotspot mutation." (PMID 39329938, 2024). "AKT1 is the main AKT subtype in tissues and cells, and is widely expressed in the membrane, cytoplasm, and nucleus of T24 and UM-UC-3 bladder cancer cells." (PMID 35111368, 2022). "Data identified that in the low HER2 cohort and different ATM levels (high/low); ABL1, SMAD4, RB1 and PARP1 were significantly upregulated and AKT1, AKT2, TSC2, RPTOR and mTOR were significantly downregulated in bladder cancer." (PMID 36056635, 2022). "RAC-alpha serine/threonine-protein kinase 1 (AKT1), glycogen synthase kinase 3 beta (GSK3B), caspase-3 (CASP3), tumor necrosis factor (TNF) and cyclin D1 (CCND1) were identified as the main hub targets of COP in bladder cancer treatment." (PMID 41287122, 2025). "In this study, through network pharmacology, it was demonstrated that AKT1, GSK3B, CASP3, TNF, and CCND1 may be the crucial targets of COP in bladder cancer treatment." (PMID 41287122, 2025). "AKT1, GSK3B, CASP3, TNF, CCND1 are the main targets of COP in the treatment of bladder cancer." (PMID 41287122, 2025). "In this section, we utilised an animal model that is more analogous to human bladder cancer to ultimately substantiate the role of NAT10 in regulating the expression of targets such as BCL9L, SOX4 and AKT1 through ac4C modification, therefore, promoting BLCA progression." (PMID 35522942, 2022). "Elevated phosphorylation of AKT1/2 is observed in 40–50% of bladder cancer cases, independent of PIK3CA or PTEN alterations, and may result from upstream receptor tyrosine kinase (e.g., FGFR3 or EGFR) activation." (PMID 41438986, 2025). "CytoNCA plug-in analysis showed that the PI3K-Akt signaling pathway (degree = 9) may be the key pathway in the treatment of bladder cancer by COP, and AKT1 (degree = 12), GSK3B (degree = 10), CASP3 (degree = 10), TNF (degree = 8) and CCND1 (degree = 8) were considered to be the main hub targets." (PMID 41287122, 2025). "this study shows clearly that mutations in AKT1 and PIK3CA are rare events and could not be considered as valuable biomarkers for bladder cancer management." (PMID 35317488, 2022).
liver cancer (170 papers, 2009 to 2026). An epithelial or non-epithelial malignant neoplasm that arises from the liver. "As the SNP was associated with liver cancer, the role of change in the expression of the AKT1 gene in LIHC was also explored." (PMID 37511907, 2023). "In order to induce liver cancer, mice were given hydrodynamic tail vein injections of plasmids to express constitutively active forms of AKT1 and NRas (SB/AKT/NRas), or AKT1 and c-Met (SB/AKT/c-Met)." (PMID 39254423, 2024). "Overexpression of activated Akt1 can only induce liver cancer development with very long latency in the mouse models." (PMID 38225233, 2024). "Our results systematically elucidate the mechanism of luteolin in inhibiting liver cancer cells, mainly through cell cycle arrest and apoptosis via targeting AKT1 and SRC." (PMID 39234106, 2024). "Single oncogene overexpression or tumor suppressor deletion is often insufficient to initiate liver cancer, e.g., activated Akt1 alone is incompetent in inducing liver cancer development." (PMID 38225233, 2024). "Our results systematically elucidate the mechanism of luteolin in inhibiting the proliferation of liver cancer cells, mainly through cell cycle arrest and apoptosis via targeting AKT1 and SRC." (PMID 39234106, 2024). "ZBTB7B bound to the promoters of known ZBTB7B targets genes, e.g., Irs1, as well as genes important in liver cancer, including Jun, Akt1, Ccnd1, and Mki67." (PMID 38225233, 2024). "AKT1 and AKT2 are widely distributed in the liver, and a recent study demonstrated that AKT1 and AKT2 mice are more susceptible to liver cancer." (PMID 36874613, 2023). "Consistently, they demonstrated that the depletion of circRNA_10156 upregulated miR-149-3p, reduced Akt1 serine/threonine-protein kinase expression, and suppressed liver cancer cell proliferation." (PMID 37958352, 2023). "Patulin, a Penicillium-derived compound, promotes ROS generation and autophagy of liver cancer cells by inactivating AKT1/mTOR, reverted by N-acetylcysteine." (PMID 36139919, 2022). "Only one study in liver cancer cells that overexpress constitutively active Akt1/PKB-α showed a 1.5-fold higher METAP2 activity compared to wildtype cells indicating that the pathway somehow regulated Metap2 activity." (PMID 35673573, 2022). "We further investigated whether continuous calcium signaling in Akt1-OE CTLs was responsible for their inability to effectively combat liver cancers." (PMID 40139836, 2025). "Functional genes, e.g., Akt1, Shc1, Prkce, Jun, and Hdac1, were highly related to each other and might play important regulatory roles in the accelerated liver cancer initiation in Zbtb7bΔli livers." (PMID 38225233, 2024). "Moreover, miR-637 has been observed to inhibit tumor cell proliferation and invasion by targeting AKT1 in liver cancer." (PMID 36329557, 2022). "As previously reported, miR-637 was downregulated in liver cancer tissues, and it could impede proliferation and invasion of liver cancer cells by targeting AKT1, serving as a cancer-suppressing agent." (PMID 34367233, 2021). "Altogether, these results indicated that circRNA_10156 could regulate liver cancer cell proliferation through the miR-149-3p/Akt1 pathway." (PMID 32624692, 2020). "Consequently, our results demonstrated that depletion of circRNA_10156 upregulated miR-149-3p, reduced Akt1 expression, and suppressed liver cancer cell proliferation." (PMID 32624692, 2020). "Inhibition of AR and/or AKT1 might serve as an effective strategy for the prevention and therapy of liver cancer." (PMID 28978011, 2017). "However, according to the proteomics analysis, chitosan nanoparticle induced the liver cancer cell to secret several proteins which may active or enhance PI3K/AKT1/mTOR pathway." (PMID 24757677, 2014). "Targeting key genes, such as AKT1, has demonstrated potential in improving lipid metabolism and inhibiting tumor growth in MASLD-related liver cancer." (PMID 41262444, 2025).
liver cancer (continued). "Network pharmacology screened 185 intersection targets of cinnamic acid and liver cancer, of which 39 core targets (such as PIK3R1, AKT1, MAPK1) were identified as key regulatory hubs through protein interaction network and topological analysis." (PMID 40872596, 2025). "Future studies should focus on the differences in the binding affinity of luteolin with AKT1 and SRC to identify the protein that functions independently in the inhibition of liver cancer when using luteolin to further enhance its use." (PMID 39234106, 2024). "The study identified AKT1, EGFR, ALB, and TNF genes as potential therapeutic targets against hepatic cancer." (PMID 39502516, 2024). "It has been reported AD activates PI3K/Akt1 and STAT3 in certain types of cells, such as the epithelial cells, the endothelial cells, and the liver cancer cells." (PMID 33815378, 2021). "The current results confirm the findings of studies identifying AKT1, CDKN2A, ERBB2, and IL6 as critical markers for metastasis of pancreatic and liver cancers." (PMID 35154607, 2021). "Using cultured liver cancer cells, we also demonstrated that AKT1 was essential for AR-induced dysregulation of AKT/mTOR signaling, metabolic reprogramming, antioxidant defense, and inflammatory responses." (PMID 28978011, 2017). "Through topological analysis (betweenness ≥ 257.821, closeness ≥ 0.00237, degree ≥ 17.195), 39 core targets were screened, including PIK3R1, AKT1, MAPK1, etc., which may play a central role in the treatment of liver cancer." (PMID 40872596, 2025). "Additionally, AD was shown to be capable of activating PI3K/Akt1 and STAT3 in some cell types, such as the epithelial cells and the liver cancer cells." (PMID 33815378, 2021). "Correspondingly, we found that overexpression of PTEN or Myr-Akt1 exhibited no influence on HIF-1α level in liver cancer cells." (PMID 34897283, 2021). "Our study demonstrated that Manilkara zapota leaf water extract upregulates JNK1 and iNOS and transcriptional downregulation of ERK1/2, Akt1, and VEGFA expression implies the potential use of Manilkara zapota leaf water extract in future applications to combat liver cancer." (PMID 30519270, 2018).